INS (insulin)
Diseases named in the same sentence as INS in open-access papers (continued):
Sharing a sentence is not in itself a finding about the gene and the disease.
Insulin resistance (continued). "According to these findings, LA metabolites PGE1 and PGE2 may increase insulin sensitivity and improve adipose insulin resistance." (PMID 39940428, 2025). "The rs10830963 variant is common and located within the single 11 kb intron of the MTNR1B gene, and the SNP has been associated with altered receptor expression or signaling efficiency, potentially leading to impaired β-cell function, reduced insulin secretion, and consequent insulin resistance." (PMID 40428319, 2025). "T2D iHeps show selective insulin resistance and cell-intrinsic insulin signaling defects." (PMID 40231468, 2025). "The combination of insulin resistance in obese patients with type 1 diabetes can lead to a misdiagnosis of type 2 diabetes, yet type 2 diabetic patients with autoimmune markers require early insulin therapy because their beta-cell function declines rapidly." (PMID 40225541, 2025). "Propionate could alleviate insulin resistance induced by a high-fat diet and improve insulin sensitivity, while sodium butyrate could prevent high-fat diet-induced insulin resistance and improve glucose homeostasis." (PMID 40329355, 2025). "Insulin resistance and impaired insulin secretion jointly characterize this stage." (PMID 41346675, 2025). "The Single Point Insulin Sensitivity Estimator for Insulin Resistance (SPISE-IR), derived from BMI, triglycerides, and HDL-c, has been validated in both pediatric and adult cohorts and shows good correlation with insulin sensitivity measured by reference methods." (PMID 40843744, 2025). "These hormones can suppress insulin signaling, contributing to insulin resistance." (PMID 40260393, 2025). "Notably, emodin demonstrates significant improvements in blood sugar regulation, weight reduction, and lowering serum insulin levels within this research context which will contribute to the improvement of insulin resistance." (PMID 40386230, 2025). "Moreover, a mutual relationship between abnormal lipid levels and reduced sensitivity to insulin (insulin resistance) has also been demonstrated." (PMID 40729034, 2025). "miRNAs may contribute to insulin resistance in MetS by influencing insulin production, mature β-cell function, and β-cell differentiation." (PMID 40565979, 2025). "However, during an acute insulin resistance induced by insulin receptor antagonist S961, glycine and β-alanine enhanced insulin secretion and reduced blood glucose levels by increasing β cell secretory capacity." (PMID 40260914, 2025). "Also, recent research highlights that insulin resistance contributes to AD pathogenesis through impaired insulin signaling, inflammation, and disrupted glucose metabolism." (PMID 40381169, 2025). "In muscle, glucotoxicity, lipotoxicity, and hyperinsulinemia promote mitochondrial ROS production, which can aggravate insulin resistance by further reducing insulin-mediated translocation of GLUT-4 transporters to the surface membrane thus contributing to the inhibition of glucose disposal." (PMID 39998445, 2025). "During insulin resistance, the body’s tissues become unresponsive to insulin’s effects despite its production, while β-cell dysfunction impairs the pancreas’s ability to secrete sufficient insulin." (PMID 40001594, 2025). "No other associations were observed between insulin-mediated changes to ATGL or HSL phosphorylation with indices of insulin resistance." (PMID 40091831, 2025). "Blautia, belonging to the phylum Firmicutes, can stimulate insulin secretion and contribute to metabolic disorders, including hypertriglyceridemia, fatty liver, and insulin resistance, which is positively correlated with waistline, body mass index, low density lipoprotein, TG and total cholesterol." (PMID 40709342, 2025). "Furthermore, adolescents with type 2 diabetes not only face greater challenges in terms of β-cell function but also exhibit significantly lower insulin sensitivity compared to adults, indicating more severe insulin resistance." (PMID 41561044, 2025).
Insulin resistance (continued). "Recently, it has been more often suggested that apelin may increase insulin sensitivity and improve insulin resistance." (PMID 40491594, 2025). "With 1μg/ml CRP-XL alone, the inhibition of PAC-1 by 10 nmol/l PGI2 in those with advanced insulin resistance was significantly reduced compared with those with normal insulin sensitivity (28 ± 9% vs 52 ± 2% p<0.001), which was also evident with higher PGI2 concentration." (PMID 40304758, 2025). "Nevertheless, future research could benefit from the adoption of more complex and accurate methods of insulin resistance assessment, such as the euglycemic clamp, which is considered the gold standard technique for quantifying insulin sensitivity." (PMID 40507609, 2025). "Although insulin, glucagon, HbA1c, and C-peptide levels remained comparable between groups, insulin resistance, as measured by HOMA-IR, increased in the Placebo group but remained unchanged in the Citrus Flavonoids group, supporting a positive metabolic effect." (PMID 40904779, 2025). "Insulin plays a key role in energy metabolism regulation, and its relationship with insulin resistance in obese patients may affect the body’s ability to efficiently process nutrients after surgery." (PMID 40284254, 2025). "Additionally, irisin levels demonstrated an inversecorrelation with insulin-related metabolic pathways, suggesting a potential role foririsin in insulin resistance states, such as obesity and T2D." (PMID 40643080, 2025). "However, in the presence of insulin resistance, these tissues require higher concentrations of insulin to respond to its effects." (PMID 39966707, 2025). "This interaction could influence insulin secretion and glucose metabolism, potentially leading to insulin resistance over time." (PMID 40649013, 2025). "Because AD is often referred to as “type 3 diabetes” due to its association with insulin resistance and IGF gene abnormalities, the ability of DHEA/DHEA-S to enhance insulin sensitivity and secretion may help reduce the risk of dementia." (PMID 41235013, 2025). "So far, as the most extensively studied metabolite of gut microbiota, short-chain fatty acids control immune-regulatory function, promote intestinal epithelial integrity, and regulate insulin secretion and pancreatic beta cell proliferation, playing multiple roles in insulin resistance and T2DM." (PMID 39611812, 2025). "Irrespective of malaria or T2DM status, glucose and insulin levels associated positively with insulin resistance." (PMID 40802820, 2025). "Briefly, prenatal treatment with BPA results in metabolic disruptions like insulin resistance and adipocyte hypertrophy in sheep, lower birthweight, adulthood obesity, impaired glucose and insulin homeostasis in mice, increased plasma triglyceride levels and adipocyte density in rats." (PMID 40914344, 2025). "Obesity-related hypoxic environments in adipocytes lead to ER stress, which downregulates adiponectin, contributing to insulin resistance.ER stress also degrades adiponectin, affecting its multimerization and stability, and further impairs its anti-inflammatory and insulin-sensitizing functions." (PMID 41567335, 2025). "The primary interaction between insulin and tyrosine kinase regulates blood glucose levels; however, an increase in Fetuin-A concentration in the bloodstream may lead to insulin resistance and, eventually, T2DM." (PMID 40141412, 2025). "In this regard, previous studies have indicated that statins may contribute to insulin resistance through a variety of mechanisms, including impaired insulin signaling, mitochondrial dysfunction, altered adipokine levels, and modification of gut microbiota." (PMID 40832614, 2025). "Moreover, the concurrent repression of insulin signaling genes is consistent with clinical observations of local insulin resistance in DFUs." (PMID 41255536, 2025).
Insulin resistance (continued). "However, fasting insulin concentrations were significantly lowered with the mango intervention compared to the control intervention, and insulin resistance status was improved, evidenced by changes in HOMA-IR and disposition index." (PMID 39940348, 2025). "Furthermore, we observed a strong association between placenta‐derived C19MC miRNAs and placental weight and UCP insulin neonatal and insulin resistance, in addition to between pregnancy‐specific C14MC miRNAs with maternal BMI and UCP leptin." (PMID 40013652, 2025). "Weight increase may trigger complex physiological and biochemical processes in the body, such as decreased insulin sensitivity and the development of insulin resistance (IR)." (PMID 41357077, 2025). "By using untargeted metabolomics with UHPLC-HRMS to profile the metabolome of IHH depending on hippurate treatment (500 μM) in insulin resistance conditions (24 h of 100 nM insulin treatment), we were able to discriminate between treatment conditions (R2Y = 0.821, Q2Y = 0.396, pQ2Y = 0.011)." (PMID 39746606, 2025). "Boys showed positive correlations between placental IRS1 expression and parameters related to body composition (weight-SDS, hip circumference, LBM, and visceral fat), while girls exhibited positive correlations with markers of insulin resistance (insulin and HOMA-IR) (all p ≤ 0.05)." (PMID 40243885, 2025). "To determine whether insulin resistance is associated with TSH-mediated macrophage infiltration and M1 polarization, we examined the changes in inflammatory cell infiltration of insulin target tissues." (PMID 40523992, 2025). "Classical features of adipocyte insulin resistance, such as reduced insulin-stimulated AKT phosphorylation or impaired downstream effects on glucose transport and lipogenesis, may therefore be present but not detectable under the basal conditions examined." (PMID 41574186, 2025). "In addition to peripheral insulin resistance, obesity impairs insulin sensitivity in the hypothalamus, where the central Resistin/TLR4 signaling axis has been implicated in promoting hypothalamic inflammation and systemic metabolic dysfunction." (PMID 41282294, 2025). "Future studies should integrate direct measures of insulin resistance, such as fasting insulin/glucose ratios or clamp techniques, to elucidate the mechanistic links between dietary macronutrient composition, cardiac insulin signaling, and functional outcomes in patients with chronic HF." (PMID 40871721, 2025). "Currently, it has been proven that the combination therapy of oral hypoglycemic agents and insulin can alleviate insulin resistance, reduce insulin dosage, avoid iatrogenic hyperinsulinemia, reduce the incidence of hypoglycemia, and achieve better glycemic control." (PMID 40114703, 2025). "Currently, the two leading hypotheses of how insulin resistance may contribute to LUTS are by insulin‐induced hyperplasia of prostate epithelial and stromal tissue (i.e. BPH) and increased prostate smooth muscle tone moderated by sympathetic nerve activity." (PMID 40955380, 2025). "Research indicates that different fat compartments affect insulin sensitivity and lipid levels differently, with excess visceral adipose tissue (VAT) posing a greater risk for insulin resistance and hyperlipidemia compared to excess subcutaneous adipose tissue (SAT)." (PMID 41446289, 2025). "In a cohort of high-risk youth with obesity, one study illustrated significant correlations between insulin resistance and elevated fasting insulin levels, further emphasizing the clinical relevance of HOMA-IR in identifying patients at risk for worsening metabolic dysfunction." (PMID 40002771, 2025). "High levels of circulating free fatty acids are deposited in insulin-sensitive non-adipose tissue cells, resulting in lip toxicity, which is an important cause of insulin resistance." (PMID 40362769, 2025).
Insulin resistance (continued). "Additionally, aging disrupts insulin-related processes, often resulting in hyperinsulinemia and insulin resistance, which can compromise immune function and promote chronic inflammation." (PMID 40176892, 2025). "Additionally, Astragalus polysaccharides can inhibit the secretion of inflammatory factors, such as resistin, which reduces the interference of inflammatory responses in insulin signaling and further ameliorates insulin resistance." (PMID 40453655, 2025). "T2DM is characterized by hyperglycemia, resulting from the inability of pancreatic β-cells to produce sufficient insulin (a hormone) and the failure of cells in muscle, fat, and the liver to take in and use enough sugar, ultimately leading to peripheral insulin resistance." (PMID 41012578, 2025). "Indeed, triglyceride infusion induces insulin resistance in both rodents and humans, while systemic inhibition of triglyceride oxidation using etomoxir improves insulin sensitivity in skeletal muscle and adipose tissue." (PMID 41155203, 2025). "Furthermore, the AE+KD group demonstrated notable improvements in insulin resistance and increased insulin sensitivity." (PMID 40948876, 2025). "Specifically, hepatic insulin resistance attenuates the inhibitory effect of insulin on gluconeogenesis, while copper accumulation abnormally activates lipid synthesis pathways such as sterol regulatory element-binding protein 1c (SREBP-1c), leading to hepatocyte lipid deposition." (PMID 40809427, 2025). "Specifically, angiotensin II reduces the metabolic actions of insulin in skeletal muscle, and insulin resistance may directly induce high blood pressure by enhancing sympathetic nervous system activity." (PMID 40283630, 2025). "Interruptions throughout the insulin signaling pathway can ultimately lead to insulin resistance." (PMID 39995417, 2025). "Consequently, insulin is unable to effectively maintain the utilization of glucose by muscles, resulting in the occurrence of insulin resistance in patients." (PMID 39911809, 2025). "However, various factors—especially chronic high-fat/high-sugar (HFD) diets, physical inactivity, and obesity—result in decreased insulin sensitivity in target organs, leading to insulin resistance, reactive hyperglycemia, and hyperinsulinemia." (PMID 41551513, 2025). "Moreover, CNIs induce peripheral insulin resistance and promote hyperglycemia by downregulating the genes that enhance insulin sensitivity in muscles and adipocytes and by reducing the number of GLUT-4 transporters in the membranes of muscle and fat cells." (PMID 39941214, 2025). "•Hippurate rescues insulin resistance induced by chronic insulin treatment." (PMID 39746606, 2025). "We find that viral-mediated induction of Rspo3 in hepatic tissue of obesity improves insulin resistance and prevents body weight gain by restoring attenuated organ insulin sensitivities, reducing adipose tissue enlargement and reversing overstimulated adaptive thermogenesis." (PMID 39854351, 2025). "However, group-by-time interaction analysis revealed that the obesity group experienced significantly greater improvements in weight, BMI, FBG, fasting insulin, and insulin resistance markers (HOMA-IR and QUICKI)." (PMID 40843316, 2025). "Moreover, insulin action on REPS1 S709 phosphorylation was impaired in several in vivo models of insulin resistance and strongly correlated with insulin sensitivity." (PMID 40482643, 2025). "However, CXCL5 in insulin-sensitive tissues, such as muscles, mediates insulin resistance through the Jak2/Stat5 signaling pathway." (PMID 40801626, 2025). "Four non-insulin-based insulin resistance (IR) markers were used to assess IR levels in patients with CKD; dietary intake – 24-h dietary recall; and diet-based acidity – potential renal acid load (PRAL), net endogenous acid production (NEAP), and dietary acid load (DAL)." (PMID 40620797, 2025).
Insulin resistance (continued). "In addition, metabolic disturbances, notably insulin resistance and dysfunction in insulin signaling, contribute to kidney dysfunction through several key signaling pathways, including PI3K/Akt, mTOR, Wnt/β-catenin, JAK/STAT, and NF-κB." (PMID 40698245, 2025). "In addition, BCVFA supplementation would increase insulin sensitivity, mitigating insulin resistance in HM cows." (PMID 39877192, 2025). "Insulin resistance (IR), characterized by the body tissue’s (including skeletal muscles, liver, and adipose tissue) reduced responsiveness to insulin, is tightly connected to and often coexists with hyperinsulinemia, a condition of excess insulin levels in the bloodstream." (PMID 40364246, 2025). "The pathophysiological mechanisms involved in the development of PTDM include increased insulin resistance, altered insulin production due to damage to pancreatic beta cells (due to inflammatory factors, oxidative stress, mitochondrial dysfunction, etc.), and uncontrolled release of glucagon." (PMID 40142909, 2025). "Ginseng and its functional components reduced fasting blood glucose (FBG) levels, fasting insulin and homeostatic model assessment for insulin resistance index (HOMA-IR) in animals of NAFLD disease model and improved glucose homeostasis, glucose tolerance and insulin tolerance in the organism." (PMID 40271056, 2025). "We add novel data to this field by demonstrating that EGP remained elevated even after adjusting for insulin levels, further suggesting hepatic insulin resistance as an important early risk factor of type 2 diabetes in Nordic women with pGDM." (PMID 40987939, 2025). "Also, obese children with vitamin D deficiency exhibited reduced insulin sensitivity (low Quantitative Insulin Sensitivity Check Index (QUICKI) and Homeostatic Model Assessment for Insulin Resistance (HOMA-IR), p=0.045)." (PMID 40585599, 2025). "Mechanistically, increased TSH levels in subclinical hypothyroidism promoted the secretion of cytokines IL-1α, IL-1β and IL-6 by inducing macrophage M1 polarization, which upregulated EGR1 to transcriptionally activate LCN2 and SOCS3 in insulin target cells, thereby exacerbating insulin resistance." (PMID 40523992, 2025). "Additionally, patients with GDM have defective pancreatic beta-cell function, unable to secrete sufficient insulin to compensate for insulin resistance." (PMID 40430234, 2025). "The HFD-fed rats had considerably increased fasting blood glucose, fasting serum insulin, Homeostatic Model Assessment for Insulin Resistance (HOMA-IR) index, and area under the curve (AUC) of oral glucose tolerance test (OGTT) compared to the control rats (p < 0.05)." (PMID 40332475, 2025). "During the phenomenon of insulin resistance, the insulin pancreatic production increases to meet the demand of chronically elevated levels of glucose in the circulation and/or the increased amount of adipose tissue that requires insulin for its glucose metabolism." (PMID 40943177, 2025). "Similarly, IL-6 contributes to insulin resistance by enhancing hepatic glucose production and reducing adiponectin levels, an anti-inflammatory cytokine critical for maintaining insulin sensitivity." (PMID 40418274, 2025). "Body weight, fasting insulin levels, and the homeostasis model assessment of insulin resistance index in the LE + HFD induction continuation group (LE + HFD-con group) were notably higher than those in the LE-con group, and ovarian histology were more severely disrupted." (PMID 40841528, 2025). "A potential mechanism behind these decreases could be the increased insulin sensitivity after BS (insulin resistance in SO alters systemic lipid metabolism)." (PMID 41160327, 2025). "At this time, insulin sensitivity is reduced due to insulin resistance." (PMID 40070584, 2025).